POMGNT1 (protein O-linked mannose N-acetylglucosaminyltransferase 1 (beta 1,2-))
Description:
Participates in O-mannosyl glycosylation by catalyzing the addition of N-acetylglucosamine to O-linked mannose on glycoproteins. Catalyzes the synthesis of the GlcNAc(beta1-2)Man(alpha1-)O-Ser/Thr moiety on alpha-dystroglycan and other O-mannosylated proteins, providing the necessary basis for the addition of further carbohydrate moieties. Is specific for alpha linked terminal mannose and does not have MGAT3, MGAT4, MGAT5, MGAT7 or MGAT8 activity.
Synonyms: GnT I.2; MGAT1.2; FLJ20277; LGMD2O; GNTI.2; LGMDR15; MEB; RP76; gnT-I.2
Tractability: Small molecule: a structure with a bound ligand is known. Antibody: UniProt predicts a signal peptide or a membrane-spanning region. PROTAC: ubiquitination databases record sites on it.
Target class: Enzyme; Transferase
Gene: Protein-coding gene on chromosome 1 (46,188,681 to 46,220,305, reverse strand). Ensembl gene ENSG00000085998.
Subcellular location: Golgi apparatus membrane
Pathways (Reactome):
Metabolism of proteins: DAG1 core M1 glycosylations; DAG1 core M2 glycosylations; Matriglycan biosynthesis on DAG1
Disease: Defective POMGNT1 causes MDDGA3, MDDGB3 and MDDGC3
Gene Ontology:
Molecular function: acetylglucosaminyltransferase activity; beta-1,3-galactosyl-O-glycosyl-glycoprotein beta-1,3-N-acetylglucosaminyltransferase activity; manganese ion binding; protein binding
Biological process: protein O-linked glycosylation; protein O-linked glycosylation via N-acetyl-galactosamine; glycoprotein biosynthetic process
Cellular component: Golgi membrane; membrane
Genetic constraint (gnomAD): Loss-of-function variants: 67 observed, 100.78 expected, observed/expected ratio (o/e) 0.66, 90% interval 0.55 to 0.81. The upper end of that interval is the gene's LOEUF score, 0.81, which puts it in group 3 of 6, group 1 being the genes least tolerant of losing a copy. Missense variants: 719 observed, 894.21 expected, observed/expected ratio (o/e) 0.8, 90% interval 0.75 to 0.86. Synonymous variants: 298 observed, 333.67 expected, observed/expected ratio (o/e) 0.89, 90% interval 0.81 to 0.98.
Gene-disease validity (ClinGen):
ClinGen rates the evidence that POMGNT1 causes each of these diseases.
myopathy caused by variation in POMGNT1 (autosomal recessive): Definitive. Any myopathy in which the cause of the disease is a variation in the POMGNT1 gene.
Homologues: Orthologues: macaque POMGNT1 (99% identical), mouse Pomgnt1 (98% identical), pig POMGNT1 (98% identical), dog POMGNT1 (98% identical), rabbit POMGNT1 (98% identical), chimpanzee POMGNT1 (96% identical), guinea pig POMGNT1 (95% identical), rat Pomgnt1 (94% identical), tropical clawed frog pomgnt1 (82% identical), zebrafish pomgnt1 (79% identical), Caenorhabditis elegans gly-14 (18% identical), Caenorhabditis elegans gly-12 (17% identical), and 1 more. Paralogues in human: MGAT1 (21% identical).
Diseases named in the same sentence as POMGNT1 in open-access papers:
POMGNT1 is named in the same sentence as 53 diseases in open-access papers, as found by Europe PMC text mining. Sharing a sentence is not in itself a finding about the gene and the disease. The quoted sentences say what the papers report.
dystroglycanopathy (20 papers, 2012 to 2026). "As shown for other genes implicated in dystroglycanopathies, it has already been suggested that the severity of the disease correlates with the strength of the disruptive effect of POMGNT1 mutations." (PMID 40244109, 2025). "Although it has been reported that several dystroglycanopathy models with mutations in POMGnT1, LARGE, or fukutin could be recovered by LARGE overexpression, laminin-binding glycans were not rescued by LARGE overexpression in AGO-deficient MEFs." (PMID 24256719, 2013). "Among POMGNT1-related α-dystroglycanopathies, muscle–eye–brain (MEB) disease presents with congenital muscular dystrophy, structural brain abnormalities, and retinal dystrophy." (PMID 40244109, 2025). "FKRP gene mutations have also been involved in α-Dystroglycanopathies together with PMOT1 (LGMDR11), FKTN (LGMDR13), PMOT2 (LGMDR14), and POMGNT1 (LGMDR15) gene mutations." (PMID 41009401, 2025). "When we queried the POMGNT1 gene in the OMIM database, we identified eye phenotypes linked to muscular dystrophy-dystroglycanopathy, in which patients have congenital glaucoma and retinitis pigmentosa." (PMID 34976016, 2021). "Another candidate experimental therapy – overexpression of the LARGE enzyme – has been shown to restore αDG function in a variety of α-dystroglycanopathies caused by mutations in FKRP, FKTN, POMGNT1 and POMT1." (PMID 32423971, 2020). "Very similar brain involvement was found in WWS patients with genetically confirmed dystroglycanopathy due to mutations in other genes like POMT2, LARGE, POMGnT1 and FUKUTIN, respectively." (PMID 31311558, 2019). "Similar results have previously been reported in dystroglycanopathy patients with Protein-O-mannosyl transferase 1 (POMT1), Protein-O-mannosyl transferase 2 (POMT2), POMGnT1, FKTN and FKRP mutations." (PMID 30553274, 2018). "Patient U1 presented with a multi-system disorder and significant myopathy; however, due to unremarkable brain imaging and a non-diagnostic muscle biopsy, the diagnosis of POMGNT1-related dystroglycanopathy was delayed." (PMID 27604308, 2016). "Previous investigators have observed altered satellite cell function in various muscular dystrophies, including DMD patients and dystroglycanopathy POMGnT1-null mice." (PMID 22887880, 2012). "Other genes contributing to dystroglycanopathies through glycosylation errors include POMT1, POMT2, POMGNT1, FKRP, ISPD and LARGE1." (PMID 38439105, 2024). "Among dystroglycanopathies, good correlation between α-DG staining and disease course was demonstrated in only a few forms (POMT1, POMT2, and POMGnT1-mutated cases), and is absent in patients with mutations in FKRP and FKTN." (PMID 26404900, 2015). "Unlike our findings, some reported patients with POMGNT1-CMD who had a reduced expression level of core α-DG; they had a normal expression level of laminin-α2, while other cases of dystroglycanopathies showed a relatively reduced leves of laminin-α2." (PMID 37318662, 2023).
Walker–Warburg syndrome (9 papers, 2006 to 2023). "Namely, POMGnT1 null mutations often cause muscle-eye-brain disease, a syndromic retinal atrophy that also manifests as brain malformations and muscular dystrophy." (PMID 36499139, 2022). "POMT2 and POMGNT1 are involved in two clinically similar disorders, respectively Walker–Warburg syndrome (WWS) and muscle–eye–brain disease (MEB)." (PMID 36859317, 2023). "Muscle, eye–brain disease (MEB) and Walker–Warburg syndrome (WWS), for example, both result from mutations in the O-linked mannose b1,2-N-acetylglucosaminyltransferase 1 (POMGnT1) gene." (PMID 36982165, 2023).
congenital muscular dystrophy (7 papers, 2018 to 2025). A muscular dystrophy that is characterized by diminished muscle tone (hypotonia), progressive muscle weakness and degeneration (atrophy), abnormally fixed joints, spinal rigidity, and delays in reaching motor milestones such as sitting or standing unassisted. "Consider that prenatal testing identified that a fetus is compound heterozygous for novel variants in the gene POMGNT1, which suggests a possible phenotype of congenital muscular dystrophy (CMD)." (PMID 29898714, 2018). "In addition, a defect in β1-2 GlcNAc-transferase (POMGNT1) has also been related to muscle–eye–brain disease characterized by congenital muscular dystrophy (CMD), ocular abnormalities and brain malformation (type II lissencephaly)." (PMID 37156804, 2023).
muscular dystrophy (7 papers, 2010 to 2022). Muscular dystrophy (MD) refers to a group of more than 30 genetic diseases characterized by progressive weakness and degeneration of the skeletal muscles that control movement. "Protein O-mannose N-acetylglucosaminyltransferase 1 (POMGnT1) knockout mice, one of the mouse models of muscular dystrophy, exhibit a thinner retina with reduced density of retinal ganglion cells." (PMID 20680099, 2010). "In the group of congenital muscular dystrophies, 11 patients received a genetic diagnosis with mutations in the following genes: LAMA2 (three cases); POMGNT1 (one case); COL6 (one case); TTN (one case); GMPPB (one case); POMT2 (one case); POMGNT2 (one case); DMD (one case); and SCGA (one case)." (PMID 34675869, 2021). "Interestingly, hypomorphic mutations in POMGnT1 have been found in retinitis pigmentosa (RP76) patients without brain malformations and muscular dystrophy, supporting that O-mannosyl glycosylation deficiency causes photoreceptor degeneration in humans." (PMID 36499139, 2022).
retinitis pigmentosa (7 papers, 2020 to 2025). Retinitis pigmentosa (RP) is an inherited retinal dystrophy leading to progressive loss of the photoreceptors and retinal pigment epithelium and resulting in blindness usually after several decades. "Recessive Protein O-linked-mannose beta-1,2-N-acetylglucosaminyltransferase 1 (POMGNT1) mutations can cause early onset muscle-eye-brain disease but have also more recently been associated with non-syndromic Retinitis Pigmentosa." (PMID 38137617, 2023). "The finding of hypomorphic POMGnT1 mutations in retinitis pigmentosa (RP76) patients supports that POMGnT1 deficiency causes photoreceptor degeneration." (PMID 32385361, 2020). "Notably, biallelic variants in POMGNT1 have also been reported to underline a rare non-syndromic form of retinitis pigmentosa (RP) (RP76, MIM #617123), highlighting an apparent phenotypic expansion of the POMGNT1-related disorders." (PMID 40244109, 2025).
muscle-eye-brain disease (6 papers, 2006 to 2023). "A final example is Muscle Eye Brain disease (MEB), caused by a mutation in the POMGnT1 gene, which is also responsible for correct glycosylation of α-dystroglycan." (PMID 32792907, 2020). "Muscular dystrophy due to hypoglycosylation of α-DG is an autosomal recessive disorder in which muscle-eye-brain disease (MEB, or muscular dystrophy-muscular dystrophy glycosis type 3A) is primarily caused by homozygous or compound heterozygous mutations in the POMGNT1 gene." (PMID 36686576, 2022).
glioblastoma (4 papers, 2021 to 2022). The most malignant astrocytic tumor (WHO grade IV). "In addition to its important role during mammalian development, POMGNT1 has recently been linked to the progression of glioblastoma, fatal primary brain tumors with survival time of 12–15 months, as well as the resistance of glioblastoma cells to the chemotherapeutic agent temozolomide." (PMID 33610554, 2021). "Further, Abbott and co-workers reported that knockdown of POMGNT1 and MGAT5B impairs neuronal cell migration, and Lan and co-workers found that silencing of POMGNT1 decreases cell proliferation and invasion in glioblastoma." (PMID 33610554, 2021). "Strikingly, in glioblastoma models, increased cell–cell adhesion has been observed when POMGNT1 is missing." (PMID 33610554, 2021). "Conversely, POMGNT1 silencing decreases cell growth and invasion in human glioblastoma cell lines." (PMID 36494657, 2022). "Interestingly, POMGNT1 is reported to be up-regulated in glioblastoma apoptosis resistant cell lines, whereas the POMGNT1 knock-down enhanced apoptosis when cells are treated with temozolomide." (PMID 34439361, 2021).
glioma (3 papers, 2021 to 2023). A benign or malignant brain and spinal cord tumor that arises from glial cells (astrocytes, oligodendrocytes, ependymal cells). "Peptide-O-linked mannose beta-1,2-N-acetylglucosaminyltransferase 1 (PomGnT1) regulates progression of glioma by activating the beta-catenin pathway and could work as a factor in the prognosis and treatment of glioma as well as a neotherapeutic molecular target." (PMID 36685667, 2023). "Very recently differential expression of POMGNT1 in human glioma cell lines has been reported to impact on the expression of some EMT marker proteins, further corroborating the general relevance and validity of our HEK293T cell model." (PMID 33610554, 2021). "Overexpression of the POMGNT1 protein has been evidenced as well in these types of advanced gliomas, its levels increasing in a correlated fashion with the degree of tumor progression (till ~ 15-fold), as a difference with grade I and II gliomas where expression of this protein was undetectable." (PMID 36494657, 2022).
Lissencephaly (2 papers, 2022). A spectrum of malformations of cortical development caused by insufficient neuronal migration that subsumes the terms agyria, pachygyria and subcortical band heterotopia. "In addition to MEB, POMGNT1 also participates in neuronal migration disorders, the lissencephaly, and the autism spectrum disorder (ASD)." (PMID 36686576, 2022).
retinal disease (2 papers, 2018 to 2025). "It has been proposed that the isolated occurrence of retinal disease in these families is likely linked to the occurrence of residual POMGNT1 catalytic activity." (PMID 40244109, 2025). "Here, we report on a family with three siblings affected by an apparently isolated clinically variable retinal disease and sharing biallelic inactivating POMGNT1 variants." (PMID 40244109, 2025). "Most interestingly, GRIPT was able to identify novel retinal disease genes, i.e., POMGNT1 (p = 2.81 × 10−10) and MFSD8 (p = 2.81 × 10−10)." (PMID 30477545, 2018). "Furthermore, GRIPT was able to identify three novel retinal disease genes recently published, i.e., POMGNT1 (p = 3.95 × 10−15), TRNT1 (p = 6.25 × 10−8) and HGSNAT (p = 2.10 × 10−7)." (PMID 30477545, 2018).
Alzheimer disease (1 paper, 2025). A progressive, neurodegenerative disease characterized by loss of function and death of nerve cells in several areas of the brain leading to loss of cognitive function such as memory and language. "The expression of POMGnT1 decreases in mouse and cell models of Alzheimer’s disease." (PMID 40709343, 2025).
Autoimmunity (1 paper, 2009). The occurrence of an immune reaction against the organism's own cells or tissues. "Our study supports this body of evidence but also extends the findings to propose new candidates governing autoimmunity that are implicated in glycosylation (Pomgnt1, Galnt11 and Galnt10)." (PMID 19915720, 2009).
Blindness (1 paper, 2021). Blindness is the condition of lacking visual perception defined as a profound reduction in visual perception. "To investigate the general validity of our findings, we took advantage of skin fibroblasts derived from an MEB patient who presented characteristic symptoms such as mental retardation and blindness due to variant c.535_751del (p.Asp179Argfs∗11) in the POMGNT1 gene (NM_017739.4)." (PMID 33610554, 2021).
diffuse large B-cell lymphoma (1 paper, 2021). "Eleven compounds are similar to Bruceine D, which appears to induce the down-regulation of POMGNT1, and is associated with improved survival in lymphoid neoplasm diffuse large B-cell lymphoma and skin cutaneous melanoma." (PMID 34439361, 2021). "Bruceine D affects POMGNT1 expression that, in turn, affects the survival in patients with lymphoid neoplasm diffuse large B-cell lymphoma and skin cutaneous melanoma." (PMID 34439361, 2021). "The survival analysis shows a high survival probability in lymphoid neoplasm diffuse large B-cell lymphoma and skin cutaneous melanoma of individuals with medium/low expression level of POMGNT1 than in individuals with high expression levels." (PMID 34439361, 2021).
Hearing impairment (1 paper, 2022). A decreased magnitude of the sensory perception of sound. "Consistent with this, it has been shown that POMGNT1 deficiency is associated with hearing impairment associated with impaired myelin formation and that POMGNT1 deficiency may lead to retinal reactive gliosis." (PMID 36686576, 2022).
myopia (1 paper, 2018). "The phenotypic subset associated with myopia (n = 130) was found to represent a set of 119 unique genes since 7 genes (COL2A1, COL11A1, FBN1, LTBP2, POMT1, POMT2, POMGNT1) had two or more associated phenotypes, leading to 11 duplicates." (PMID 29346494, 2018).
retinal detachment (1 paper, 2025). An eye emergency condition which may lead to blindness if left untreated. "Variants in the POMGNT1 gene in humans cause muscle–eye–brain disease (MEB), which is associated with several ocular abnormalities; retinal dysplasia, ERG abnormalities, and retinal detachments have been reported in patients." (PMID 40428427, 2025).
Retinal dystrophy (1 paper, 2025). Retinal dystrophy is an abnormality of the retina associated with a hereditary process. "Here, we describe three affected siblings showing biallelic LoF POMGNT1 variants, sharing non-syndromic retinal dystrophy." (PMID 40244109, 2025). "The description of an additional cohort of patients with non-syndromic retinal dystrophy related to POMGNT1, traditionally causative of MEB disease, emphasizes the need for broader genetic testing, especially in patients with verified isolated retinal dystrophy and nonconclusive genotype." (PMID 40244109, 2025).
Ventriculomegaly (1 paper, 2018). An increase in size of the ventricular system of the brain. "Similarly, the fetuses with the POMGNT1 homozygous missense variant had presented with ventriculomegaly, an early feature of muscle‐eye‐brain disease (case 28)." (PMID 29096039, 2018).
brain disease (6 papers, 2017 to 2025). "In addition, abnormally glycosylated DAG also causes mutation in POMGnT1, which leads to an autosomal recessive disorder, called muscle–eye–brain disease." (PMID 30410234, 2018). "The protein O-mannose beta-1,2-N-acetylglucosaminyltransferase 1 (POMGNT1) gene is one of 18 genes involved in the pathogenesis of α-dystroglycanopathies(α-DGPs) such as muscle–eye–brain disease (MEB)." (PMID 28765568, 2017).
tumor (5 papers, 2013 to 2025). "Interestingly, POMGNT1 seems to be positively associated with high nuclear grade and tumor stage." (PMID 26220087, 2015). "On the other hand, a series of other genes acting earlier in this pathway are overexpressed in tumor cells, namely DOLK, DPM1/2/3, POMGNT1, B3GALNT2, POMK and FKTN, hence exerting instead a pro-oncogenic role." (PMID 36494657, 2022).
cancer (3 papers, 2021 to 2022). A tumor composed of atypical neoplastic, often pleomorphic cells that invade other tissues. "The gene POMGNT1 is down-regulated under Al-10-49 apoptotic treatment and in Bruceine D nutrigenomics treatment, while it is up-regulated in 4 different cancer types." (PMID 34439361, 2021). "Similar expression of POMGNT1 and B3GAT3 was observed in normal versus cancer tissues by immunohistochemical staining." (PMID 35356430, 2022).
inherited diseases (1 paper, 2017). "To conclude, this study revealed how NGS can identify the CNV of MEB and other inherited diseases, and three novel mutations in POMGNT1 were reported, which significantly expanded the mutation spectrum of MEB." (PMID 28765568, 2017).
POMGNT1 also shares sentences with these, for which no sentence is quoted: cobblestone lissencephaly (2 papers); neurological disorders (2); retinal degeneration (2); Angelman syndrome (1); Anxiety (1); autism spectrum disorder (1); brain malformations (1); Cerebellar hypoplasia (1); CHARGE syndrome (1); congenital glaucoma (1); congenital myopathies (1); Down syndrome (1); Intellectual disability (1); Knobloch syndrome (1); limb-girdle muscular dystrophy (1); lymphoid neoplasm (1); Marfan syndrome (1); microcephalic osteodysplastic primordial dwarfism type II (1); myopathy (1); Noonan syndrome (1); optic atrophy (1); pancreatic cancer (1); Parkinsonism (1); polymicrogyria (1); Prader-Willi syndrome (1); Retinal atrophy (1); Retinal dysplasia (1); retinitis pigmentosa 76 (1); Seizure (1); skin cutaneous melanoma (1).